ZNFX1 (zinc finger NFX1-type containing 1)
Description:
RNA-activated non-canonical E3 ubiquitin ligase required for cell survival during interferon (IFN) responses. Functions as an ATP-dependent 5'-> 3' RNA translocase that selectively recognizes long single-stranded RNA (ssRNA) molecules (>100 nt) from viral or host origin during immune activation. Upon ssRNA binding, oligomerizes to assemble a split E3 active site in trans, involving the Z-RING domain that binds and activates E2-ubiquitin conjugates, such as UBE2D2, and the RZ catalytic domain that mediates ubiquitin transfer. Catalyzes hydroxyl ubiquitination of the 2'-OH of ssRNA ribose and auto-ubiquitination, generating mainly 'Lys-48'- and 'Lys-6'-linked polyubiquitin chains. Forms ubiquitin-coated RNA condensates and stress granules, thereby regulating RNA metabolism, limiting excessive immune signaling, and preventing IFN-induced cell death. Also required for immunity against some bacteria, such as mycobacteria. Inhibits NLRP3 inflammasome activation by sequestering NLRP3 in the cytoplasm and preventing its translocation to trans-Golgi network vesicles during the resting state. Upon inflammasome activation, is cleaved by CASP1, establishing a feed-forward loop that amplifies NLRP3 inflammasome activity.
Synonyms: KIAA1404; FLJ11277; IMD91
Tractability: PROTAC: ubiquitination databases record sites on it; its protein half-life has been measured.
Gene: Protein-coding gene on chromosome 20 (49,237,946 to 49,278,426, reverse strand). Ensembl gene ENSG00000124201.
Subcellular location: Mitochondrion outer membrane; Cytoplasm, Stress granule; Cytoplasm, cytosol
Subcellular location (Human Protein Atlas): Mitochondria
Gene Ontology:
Molecular function: protein sequestering activity; RNA binding; helicase activity; ubiquitin protein ligase activity; zinc ion binding
Biological process: defense response to bacterium; defense response to virus; negative regulation of NLRP3 inflammasome complex assembly; activation of innate immune response; negative regulation of viral genome replication; regulatory ncRNA-mediated heterochromatin formation
Cellular component: cytoplasmic stress granule; cytosol; mitochondrial outer membrane; nuclear RNA-directed RNA polymerase complex; cytoplasm; nucleus
Genetic constraint (gnomAD): Loss-of-function variants: 71 observed, 177.06 expected, observed/expected ratio (o/e) 0.4, 90% interval 0.33 to 0.49. The upper end of that interval is the gene's LOEUF score, 0.49, which puts it in group 2 of 6, group 1 being the genes least tolerant of losing a copy. Missense variants: 1,863 observed, 2,413.7 expected, observed/expected ratio (o/e) 0.77, 90% interval 0.74 to 0.8. Synonymous variants: 816 observed, 888.36 expected, observed/expected ratio (o/e) 0.92, 90% interval 0.87 to 0.97.
Homologues: Orthologues: chimpanzee ZNFX1 (99% identical), macaque ZNFX1 (98% identical), dog ZNFX1 (91% identical), guinea pig ZNFX1 (90% identical), pig ZNFX1 (89% identical), rabbit ZNFX1 (89% identical), mouse Znfx1 (88% identical), rat Znfx1 (87% identical), tropical clawed frog znfx1 (59% identical), zebrafish znfx1 (39% identical), Drosophila melanogaster CG6204 (14% identical), Caenorhabditis elegans eri-7 (7% identical), and 2 more. Paralogues in human: AQR (11% identical), HELZ2 (10% identical), HELZ (10% identical), IGHMBP2 (10% identical), SETX (10% identical), MOV10L1 (9% identical), MOV10 (8% identical), DNA2 (8% identical), UPF1 (8% identical), CT55 (1% identical).